SHBG (sex hormone binding globulin)
Diseases named in the same sentence as SHBG in open-access papers (continued):
Sharing a sentence is not in itself a finding about the gene and the disease.
breast cancer (continued). "The MR Egger analyses supported the causality of female T to ER+ breast cancer (β = 0.282, p = 0.00014 for total T), whereas prostate cancer risk was linked to SHBG levels (GCP = −0.64, p = 0.00019)." (PMID 36653534, 2023). "In postmenopausal women, increased adiposity leads to increased oestrogen synthesis and reduced circulating sex-hormone binding globulin, leading to higher levels of bioavailable oestradiol, which is positively associated with breast cancer risk." (PMID 35255844, 2022). "Using two-sample MR, recent studies have reported a 7% reduction in breast cancer risk and a 9% reduction in prostate cancer risk per 1 SD (25 and 30nmol/L) increase in SHBG, respectively." (PMID 35061662, 2022). "Other biomarkers such as BMI, neutrophil count, IGF-1, testosterone and sex hormone-binding globulin (SHBG) were also associated with breast cancer risk, but the ORs were below 1.2." (PMID 35578620, 2022). "Genetically predicted alkaline phosphatase remained nominally significantly associated with overall breast cancer liability after adjusting for testosterone and SHBG in MVMR (OR: 0.94, 95% CI: 0.89–0.98)." (PMID 36424572, 2022). "We further confirmed that high circulating testosterone and low SHBG levels were associated with an increased risk of breast cancer in our study, likely due to aromatase activity in fat tissues for testosterone and the binding effect of SHBG with estrogen." (PMID 35578620, 2022). "The previous study also reported reduced risk of ER-positive (OR = 0.91, 95% CI: 0.82, 1.01) and increased risk of ER-negative (OR = 1.14, 95% CI: 1.01, 1.28) breast cancer per SD increase in SHBG." (PMID 35061662, 2022). "This study confirms associations of testosterone, IGF-1 and SHBG with breast cancer risk, with heterogeneity by menopausal status for testosterone." (PMID 33864017, 2021). "Previous studies have consistently shown that higher SHBG levels decrease the risk of breast cancer in postmenopausal women." (PMID 32895915, 2021). "Circulating estrogens, androgens, and insulin-like growth factor 1 (IGF-1) have been associated with an increased risk of breast cancer in women, whereas sex hormone-binding globulin (SHBG) is inversely associated with the risk." (PMID 34607837, 2021). "In post-menopausal women, there was a significant inverse association between SHBG and breast cancer risk (HR per 30 nmol/L increment: 0.89; 95% CI: 0.84, 0.94)." (PMID 33864017, 2021). "Sex hormone binding globulin (SHBG) is a major biomarker of breast cancer risk, diagnosis and prognosis." (PMID 32085420, 2020). "High levels of sex serum hormones, including estrogens and androgens, and low levels of sex hormone binding globulin (SHBG) are associated with higher postmenopausal breast cancer risk." (PMID 30071893, 2018). "Higher early pregnancy testosterone and SHBG were associated with higher breast cancer risk (testosterone, third vs first tertile OR(T3–T1): 1.46 (95% CI: 0.96–2.21), ptrend = 0.04; SHBG: 1.68 (1.05–2.70), ptrend = 0.13)." (PMID 28720108, 2017). "The risk for breast cancer increased significantly with increasing concentrations of all sex hormones examined: total estradiol, free estradiol, non-SHBG-bound estradiol, estrone, estrone sulfate, and testosterone." (PMID 25115686, 2014). "Following CEE treatment, breast cancer risk was associated with higher concentrations of baseline serum estrogens, and with lower concentrations of sex hormone binding globulin." (PMID 24670297, 2014). "In this prospective study of premenopausal plasma sex steroids and SHBG and breast cancer risk, we found positive associations between androgens and risk of both invasive and ER+/PR+ breast cancer, as well as luteal estradiol and risk of ER+/PR+ tumors." (PMID 23497468, 2013). "We evaluated associations between mid-luteal total and free testosterone (FT), estradiol, progesterone, and sex hormone-binding globulin (SHBG) and premenopausal breast cancer risk." (PMID 23777922, 2013).
breast cancer (continued). "For example, the D327N variant of the sex hormone-binding globulin (SHBG) which creates a new glycosylation site was shown to be protective in breast cancer." (PMID 22586465, 2012). "This presumably accounts for the reduced risk of breast cancer observed in most studies among women with the highest SHBG levels." (PMID 22675492, 2012). "Results suggest that premenopausal women with elevated serum total and non-SHBG-bound testosterone levels are at an increased risk of subsequent breast cancer." (PMID 21087481, 2010). "Adjustment for MIS attenuated only slightly the associations of total and non-SHBG-bound testosterone with breast cancer risk." (PMID 21087481, 2010). "The apparently positive association between SHBG levels and percentage breast density or dense area seems in contradiction with the inverse relation between these SHBG levels and breast cancer risk that has been described in many epidemiologic studies." (PMID 17692133, 2007). "Notably, this genetic panel (nine loci linked to SHBG levels) has been previously investigated in our studies of breast cancer and endometriosis." (PMID 40724651, 2025). "Niki Dimou found that SHBG levels are negatively correlated with breast cancer risk." (PMID 39687887, 2024). "Consequently, a decrease in SHBG levels is associated with a higher risk of breast cancer development." (PMID 39548533, 2024). "Regarding other estrogens and androgens (including estrone, androstenedione, dehydroepiandrosterone, and testosterone), a similar extent of increased breast cancer risk has been observed, while an inverse association has been shown for sex hormone-binding globulin (SHBG)." (PMID 38892081, 2024). "In our “top list” of the 36 most important findings, high breast density had the highest effect size for increasing the risk of breast cancer, and a high sex-hormone-binding globulin level was identified as the most protective factor in decreasing breast cancer risk." (PMID 38672665, 2024). "Because only the impact of SHBG on the therapeutic effect and recurrence risk of breast cancer during and after endocrine therapy needs to be analyzed, this is beneficial for clarifying the correlation between SHBG changes and endocrine therapy resistance of ER-positive breast cancer." (PMID 38465341, 2024). "Moreover, the molecular mechanisms by which SHBG affects breast cancer risk are also summarized in detail." (PMID 38465341, 2024). "Additionally, the molecular mechanisms by which SHBG affects breast cancer risk are also summarized in detail." (PMID 38465341, 2024). "This review shows some recent studies involving plasma SHBG levels and breast cancer risk." (PMID 38465341, 2024). "Increased breast density and bone density, never having married, higher BMI, and meat consumption were risk factors for breast cancer, and high sex-hormone-binding globulin levels, progestin, physical activity, and higher BMI were the most protective factors, and at the top of our list." (PMID 38672665, 2024). "In addition, existing studies have focused on the morbidity of overall breast cancer, suggesting that low SHBG levels increase the risk of breast cancer compared to controls." (PMID 38465341, 2024). "Previous studies declared that any genetic variant decreasing the levels of SHBG would allow more free estradiol to circulate and hence could increase the risk of diseases associated with increased free estradiol levels (e.g., breast cancer)." (PMID 39054435, 2024). "Oestradiol (−0.08 [−0.15: −0.02]) and SHBG (−0.19 [−0.29: −0.08]) were both inversely affected by increased childhood body size, but there was limited evidence of them affecting the risk of breast cancer (OR: 0.96 [0.68: 1.34] and OR: 0.97 [0.91: 1.04], respectively)." (PMID 35396499, 2022). "Additionally, a Mendelian randomization study also suggested SHBG as a causal factor for breast cancer." (PMID 35578620, 2022).
breast cancer (continued). "Using two-step MR, we identified IGF-1, SHBG, testosterone, age at menarche and age at menopause as plausible mediators based on the effect of childhood body size on these traits, and their effect on breast cancer risk." (PMID 35396499, 2022). "In summary, we found a positive association of breast cancer risk with testosterone in post-menopausal women; an inverse association of risk with SHBG in post-menopausal women; and a positive association of risk with IGF-1 in both pre- and post-menopausal women." (PMID 33864017, 2021). "SHBG regulates the bioavailability of free estrogens, which if unbound, are considered to be highly active and associated with increased risk of some hormone‐sensitive cancers, particularly breast cancer." (PMID 32741068, 2021). "Notably, high levels of SHBG have been shown to be inversely associated with breast cancer risk in large meta-analyses of prospective studies." (PMID 33767162, 2021). "SHBG is a serum glycoprotein that binds oestrogens and androgens with high affinity and specificity, thereby lowering the bioavailable fraction of these sex steroids and potentially reducing subsequent breast cancer risk." (PMID 33864017, 2021). "It has been shown that breast cancer risk is inversely correlated with blood levels of SHBG." (PMID 30717356, 2019). "Smoking may enhance the metabolism of estradiol, increase the binding of estrogens by serum sex hormone-binding globulin, and lower the levels of estrogen derived from adipose tissue thus leading to a decreased risk of breast cancer." (PMID 27055053, 2016). "Similarly, high adiposity was linked to low levels of sex steroid hormone binding globulin (SHBG), a protein responsible for binding of the sex steroid hormones, while up-regulation of SHBG level was associated with reduced risk of breast cancer." (PMID 26694341, 2015). "One of the pathways by which these lifestyle factors may influence postmenopausal breast cancer risk is through effects on serum sex hormones (i.e., oestrogens, androgens and the protein sex hormone-binding globulin [SHBG])." (PMID 26330303, 2015). "We showed that 1 gm of resveratrol daily for 12 weeks did not alter the serum estrogen and testosterone concentrations in postmenopausal women with high adiposity but significantly increased the concentrations of SHBG, which has been inversely associated to breast cancer risk." (PMID 25115686, 2014). "As exposure to high circulating estradiol and testosterone, and low sex hormone-binding globulin (SHBG) levels is implicated in breast cancer etiology, we conducted GWAS analyses of plasma estradiol, testosterone, and SHBG to identify new susceptibility alleles." (PMID 22675492, 2012). "Therefore, it is unlikely that, individually, other common variants that influence plasma estradiol, testosterone, or SHBG levels among postmenopausal women to the same or lower extent than that identified in our study will predict breast cancer risk." (PMID 22675492, 2012). "Whilst the effects of these variants on circulating levels of SHBG and estradiol are evidently large enough to be directly detectable, it appears that they do not change levels by a sufficient amount to have a detectable effect on breast cancer risk." (PMID 22675492, 2012). "However, adjustment for MIS in the current analysis attenuated associations of total and non-SHBG-bound testosterone with breast cancer only slightly, and women in the highest quartiles remained at significantly increased risk." (PMID 21087481, 2010). "Although testosterone and SHBG concentrations were associated with breast cancer risk, the concentrations of these hormones were correlated with those of oestradiol; the associations were not statistically significant after adjusting for oestradiol concentration." (PMID 9252211, 1997).
breast cancer (continued). "The sex hormone-binding globulin protein, regulating the bioavailability of hormones like testosterone and estrogen, was found to be implicated in various types of cancers–particularly hormone-related cancers such as prostate and breast cancers–particularly when it is downregulated." (PMID 40565234, 2025). "Furthermore, the Reach for Health study demonstrated that improved glycaemic control achieved via metformin therapy and weight loss had a positive impact on the plasma insulin, SHBG and oestrogen concentrations in postmenopausal breast cancer survivors who were either overweight or obese." (PMID 37047163, 2023). "In addition, high serum sex hormone-binding globulin (SHBG) concentrations may reduce the risk of breast cancer, while serum IGF-1 levels may be positively associated with the risk." (PMID 38000092, 2023). "In postmenopausal women risk of estrogen receptors-positive breast cancer development is inversely related to blood levels of SHBG, reply to endometrial cancer in which was reported an increased cancer risk among both pre and postmenopausal women who have comparatively low plasma levels of SHBG." (PMID 27029038, 2016). "In summary, post-treatment changes in serum estrogens and SHBG concentrations, or changes in the association of such concentrations with disease risk, have the potential to substantially explain both the elevation in breast cancer risk with CEE + MPA and the reduction in risk with CEE." (PMID 24670297, 2014). "A secondary analysis investigated the effect of the baseline testosterone/SHBG ratio on breast cancer development." (PMID 40973715, 2025). "In this pre-planned study, the primary endpoint was the effect of the anastrozole on all breast cancers, including ductal carcinoma in situ via a reduction of unbound oestradiol, as assessed by the oestradiol/SHBG (E2/SHBG) ratio." (PMID 40973715, 2025). "It has been found in in vitro studies that phytoestrogens, like estrogens, bind to estrogen receptors and increase the synthesis of SHBG by liver cells, but, like anti-estrogens, they inhibit aromatase activity and breast cancer cell proliferation." (PMID 40218942, 2025). "One of these three genes, SNX13 (Sorting Nexin 13), was associated with both post-AI E2 levels in the M3 cohort as well as sex-hormone binding globulin levels, which are likely to be relevant to breast cancer." (PMID 38965614, 2024). "Perhaps because breast cancer is the most common malignancy in women and also the most common sex hormone-dependent tumor, SHBG and breast cancer have been significantly more studied than the latter two cancers." (PMID 38465341, 2024). "The expression level of SHBG protein in primary breast cancer is lower than that in normal tissue (p < 0.001), regardless of breast cancer subclass (all p < 0.001)." (PMID 38465341, 2024). "Specifically, when DIM was used in tandem with tamoxifen, the ratio between 2OHE1/16αOHE1 increased up to 229%, as well as the concentration of the sex hormone binding globulin (SHBG) that inhibits the growth of breast cancer cells." (PMID 38410780, 2024). "Sex Hormone-Binding Globulin (SHBG) also plays a crucial role in the pathophysiology of breast cancer, primarily by regulating circulating estradiol." (PMID 39548533, 2024). "For instance, elevated levels of testosterone and CRP (C-reactive protein) are linked to increased breast cancer risk, whereas higher levels of SHBG (sex hormone-binding globulin) are associated with reduced risk." (PMID 39791640, 2024). "This article reviews the clinical significance of changes in circulating SHBG levels in the development of breast cancer and the possible influence of these levels on endocrine drug resistance in hormone receptor-positive breast cancer." (PMID 38465341, 2024). "Elevated levels of SHBG have been observed in certain types of cancer, including prostate cancer, breast cancer, and ovarian cancer." (PMID 37538932, 2023).
breast cancer (continued). "SIMEX corrections were conducted for SHBG effect on breast cancer which were found to be consistent with MR Egger results reported in the main analyses." (PMID 35061662, 2022). "In Radial MR there were five, three and three SNPs identified as potential influential outliers in the main IVW analyses of total testosterone, bioavailable testosterone and SHBG on breast cancer, respectively." (PMID 35061662, 2022). "The other reason contributing to progression of breast cancer is decrease of plasma levels of sex hormone binding globulin related to insulin, which results in increase of endogenous estrogen and androgen levels." (PMID 35582045, 2020). "Sex hormones have an important role in the etiopathogenesis of mammary cancer, and sex hormone binding globulin modulates the functions of testosterone and estradiol, changing their bioavailability in the organism." (PMID 31703601, 2019). "SHBG binds to breast cancer cells to inhibit estradiol-induced cell proliferation, and incubation of breast cancer cells with SHBG before treatment with estradiol cancels out the anti-apoptotic effect of estradiol." (PMID 30717356, 2019). "Unregulated estrogen production, in combination with reductions of SHBG, increases free estradiol among overweight/obese postmenopausal women promoting the development of breast cancer, particularly hormone receptor-positive subtypes." (PMID 26352264, 2015). "In our study the serum level of steroid hormones, hormone-precursors and SHBG were measured prior to surgical intervention in postmenopausal women with primary breast cancer." (PMID 26240785, 2015). "In breast cancer, insulin induces aromatase activity and reduces sex hormone binding globulin (SHBG), leading to increased free oestrogen levels, which in turn increases mitogenicity." (PMID 26541196, 2015). "We evaluated the associations between estrogens, androgens, progesterone and sex hormone binding globulin (SHBG) and breast cancer in a nested case-control study in the Nurses' Health Study II." (PMID 23497468, 2013). "Intracellular expression of SHBG was detected in breast cancer cell line MCF-7 both in mRNA level by real-time PCR and protein level by Western blotting, and it was proved to be dose-dependent of estrogen in the cell culture medium." (PMID 24386165, 2013). "Here, we examined relationships between the serum levels of tamoxifen, estrogens, follicle-stimulating hormone (FSH), and sex hormone-binding globulin (SHBG) in postmenopausal breast cancer patients." (PMID 20565970, 2010). "In postmenopausal women with breast cancer, tamoxifen treatment resulted in increased sex hormone binding globulin and decreased levels of circulating androgens." (PMID 16970814, 2006). "Accordingly, the increased risk of breast cancer in postmenopausal women who gain large amounts of weight or are overweight is attributed to excess plasma levels of oestrogens, together with low levels of sex-hormone-binding globulin (SHBG)." (PMID 16136032, 2005). "The associations between serum concentrations of oestradiol, testosterone and sex hormone-binding globulin (SHBG) and risk of breast cancer in post-menopausal women were investigated in a prospective study on the island of Guernsey." (PMID 9252211, 1997). "Free E2 and SHBG were also measured in the serum of (e) postmenopausal patients having breast cancer (n = 38) and (f) matched control cancer patients (n = 67)." (PMID 4038881, 1985). "Additionally, women diagnosed with breast cancer and women with a family history of breast cancer should have their levels of SHBG tested due to the effect of this protein on the occurrence of ER(+) and ER(-) BCs." (PMID 40427034, 2025).